MTSS1 (MTSS I-BAR domain containing 1)
Diseases named in the same sentence as MTSS1 in open-access papers (continued):
Sharing a sentence is not in itself a finding about the gene and the disease.
prostate carcinoma (continued). "Importantly, introducing wild-type MTSS1 or a mutated non-degradable MTSS1 (MTSS1/S322A) into breast or prostate cancer cells with low wild-type MTSS1 expression significantly inhibited cellular proliferation and migration." (PMID 39625546, 2024). "Also knock down of miR-182-5p in order to increase expression of tumor suppressor genes FOXF2, RECK and MTSS1 may be of therapeutic benefit in prostate cancer treatment." (PMID 23383207, 2013). "Additionally knocking down of miR-182-5p with inhibitor may be of therapeutic benefit for enhancing expression of tumor suppressor genes FOXF2, RECK and MTSS1 in prostate cancer cells." (PMID 23383207, 2013). "Inhibition of miR-182-5p by an inhibitor of this microRNA also resulted in the suppression of invasion and migration in prostate cancer cells via upregulation of FOXF2, RECK, and MTSS1." (PMID 37438760, 2023). "Our data show that, like in prostate cancer and CML, promoter methylation contributes to the regulation of MTSS1 in primary AML samples and AML cell lines." (PMID 33782537, 2021). "In-vitro studies showed that the knock-down of miR-182-5p in prostate cancer cell can promote cell proliferation, migration and invasion by regulating the potential targets of FOXF2, RECK and MTSS1." (PMID 32102688, 2020). "Since we focused on three target genes (RECK, MTSS1 and FOXF2) and investigated only 52 clinical samples, additional studies will be needed to elucidate the role of miR-182-5p in prostate cancer and its use in clinical applications." (PMID 23383207, 2013). "Introducing wild-type MTSS1 or a non-degradable MTSS1 into breast or prostate cancer cells with low levels of MTSS1 inhibited cell proliferation and migration." (PMID 27206673, 2016). "Our study suggests that at least in the breast or prostate cancer settings, β-TRCP overexpression could possibly lead to increased degradation of the tumor suppressor MTSS1, thereby contributing to tumorigenesis." (PMID 24318128, 2013).
hepatocellular carcinoma (16 papers, 2010 to 2023). A malignant tumor that arises from hepatocytes. "Metastatic suppressor 1 (MTSS1) is a potential target of miR-141-3p that promotes HBV-related hepatoma cell migration associated with poor prognosis." (PMID 36203765, 2022). "In recent years, studies have found that MTSS1 exhibits tissue-specific expression, and increased MTSS1 expression has been associated with tumorigenesis in certain other types of malignant tumor, such as hepatocellular carcinoma, colorectal cancer, and head and neck squamous cell carcinoma." (PMID 25295101, 2014). "In human hepatocellular carcinoma, the overexpression of DNMT3B was negatively associated with MTSS1 (metastasis suppressor 1) expression." (PMID 37233501, 2023). "MTSS1 had been previously considered a potential tumor suppressor in various cancers, but as an oncogene in hepatocellular carcinomas." (PMID 35768865, 2022). "Many studies have found that loss of MTSS1 is detrimental to patient survival and prognosis; however, in both colorectal and hepatocellular carcinoma, data show that elevated MTSS1 is an indicator of poor prognosis." (PMID 28146435, 2017). "However, recent studies found MTSS1 is also highly expressed in some solid tumors such as hepatocellular carcinoma (HCC)." (PMID 36496997, 2022). "DNMT3B binding to the MTSS1 promoter has previously been described to occur at -864/-645 bp upstream of the transcriptional start site and acts as a mechanism that allows for transcriptional suppression of MTSS1 in hepatocellular carcinoma." (PMID 25996952, 2015). "This indicates that MTSS1 may be involved in cervical cancer invasion and metastasis, a finding consistent with those from studies regarding hepatocellular carcinoma and colorectal cancer tissues." (PMID 25295101, 2014). "In addition miR-182 has been reported to down-regulate MTSS1 and promote metastasis of hepatocellular carcinoma, a result very similar to ours." (PMID 23383207, 2013). "Specifically, a higher level of MTSS1 expression was observed at the early stages of the disease, suggesting that MTSS1 may play an important role in promoting the early development of hepatocellular carcinoma." (PMID 20712855, 2010). "However, another report reveals that an incremental increase in MTSS1 expression was detected from healthy normal liver donors to non tumor tissue specimens and then to their matched hepatocellular carcinoma tumor tissue specimens." (PMID 20712855, 2010).
bladder cancer (15 papers, 2010 to 2024). "In bladder cancer, MAEL plays a critical oncogenic role in supporting cell EMT and invasion and bladder cancer metastasis via downregulation of MTSS1 through DNMT3B." (PMID 35513870, 2022). "MAEL has different molecular mechanisms in different tumor types in which it activates the AKT/GSK-3b/SNAIL signaling in HCC, inhibits the E-cadherin in CRC, inhibits the MTSS1 in bladder cancer, and inhibits ILKAP tumor suppressor in GC." (PMID 33902648, 2021). "MTSS1 DNA methylation and transcriptional silencing has been reported in bladder cancer cells, with detection of a promoter activity region 276 bp upstream of the metastasis suppressor protein 1 (MTSS1) gene within a CpG island." (PMID 31013819, 2019). "Functional analysis revealed that MTSS1, which was initially described as a gene missing in invasive bladder cancer cell lines, was an actin binding protein involved in the regulation of actin cytoskeleton dynamics." (PMID 26705104, 2015). "MTSS1 (metastasis tumor suppressor-1) was initially identified as a tumor suppressor gene in bladder cancer." (PMID 23383207, 2013). "Finally, MAEL plays a key oncogenic role in bladder cancer by downregulating MTSS1." (PMID 33193734, 2020). "MTSS1, also called Missing in Metastasis (MIM), was originally identified in human bladder cancer cell lines." (PMID 39404373, 2024). "Mtss1 was identified as a potential tumor suppressor as it was not expressed in human bladder cancer cell lines and involved in signaling in other carcinomas." (PMID 26576534, 2015). "MTSS1 might act as a putative tumor suppressor in human bladder cancer where MTSS1 could not be detected by immunohistochemistry." (PMID 22926221, 2012).
ovarian carcinoma (11 papers, 2014 to 2025). A malignant neoplasm originating from the surface ovarian epithelium. "To explore the role of MTSS1 in ovarian cancer, we knocked down MTSS1 by siRNA and overexpressed it by overexpression plasmids in A2780 and MDAH2774 ovarian cancer cells." (PMID 35768865, 2022). "Some microRNAs were reported to regulate MTSS1 in other cancer types such as miR-96-5p in ovarian cancer and miR-23a in colorectal cancer." (PMID 36496997, 2022). "Taken together, our data revealed a working model that circFBXO7 inactivates Wnt/β-catenin signaling pathway by regulating the miR-96-5p/MTSS1 axis in ovarian cancer cells." (PMID 35768865, 2022). "Further rescue experiments revealed that circFBXO7 can modulate MTSS1 by competitively sponging miR-96-5p to inhibit ovarian cancer cell proliferation and metastasis." (PMID 35768865, 2022). "While the expression of MTSS1 is significantly reduced in melanoma, testicular, lung and ovarian cancers, the levels are higher in certain cancer types of brain and kidney tissues, for example." (PMID 30858428, 2019). "Our results support the view that down-regulated blood cell MTSS1 expression is a marker of worse prognosis in ovarian cancer." (PMID 24961659, 2014). "Overexpression of circFBXO7 in ovarian cancer cells can increase the level of MTSS1 by downregulating the level of miR‐96‐5p, inducing the accumulation and nuclear transport of β‐catenin, as well as phosphorylation of GSK3β, ultimately leading to the deterioration of ovarian cancer." (PMID 39584047, 2024). "This suggests that circFBXO7 may regulate the occurrence and development of ovarian cancer through the circFBXO7/miR-96-5p/MTSS1 axis." (PMID 35768865, 2022). "Furthermore, transfection with miR-96-5p mimics or MTSS1 siRNA in ovarian cancer cells with circFBXO7 overexpression was able to dramatically rescue the suppressed Wnt signaling activation caused by overexpression of circFBXO7." (PMID 35768865, 2022). "MTSS1 in turn, is a target of miR-96-5p, and plays a tumor suppressive role in ovarian cancer." (PMID 35768865, 2022). "In addition to the partial regulation of β-catenin by phosphorylated GSK3β, there may be other downstream factors regulated by circFBXO7/MTSS1 to regulate β-catenin expression or promote β-catenin nuclear translocation in ovarian cancer cells." (PMID 35768865, 2022). "Our findings indicate that circFBXO7 acts as a bone fide tumor suppressor in ovarian cancer and that the circFBXO7/miR-96-5p/MTSS1 axis is an important regulator in the Wnt/β-catenin signaling pathway which may provide a promising target for ovarian cancer therapy." (PMID 35768865, 2022). "Consequently, downregulation of MTSS1 led to excessive accumulation of β-catenin and increased phosphorylation of GSK3β, leading to the translocation of β-catenin to the nucleus, thereby activating the Wnt/β-catenin signaling pathway and ultimately promoting ovarian cancer progression." (PMID 35768865, 2022). "It has also been shown that LYAR, PDIA3, NOP14, NCALD, MTSS1 and CYP1B1 are correlated with the prognosis of ovarian cancer." (PMID 34696677, 2021). "In addition, LYAR and five other genes (PDIA3, NOP14, NCALD, MTSS1, and CYP1B1) showed potential as prognostic biomarkers for radical ovarian cancer." (PMID 34696677, 2021). "A gene expression profile study with whole blood cell mRNA from ovarian cancer patients revealed LYAR and other five genes (PDIA3, NOP14, NCALD, MTSS1 and CYP1B1) as potential prognostic biomarkers for curative and postoperative supportive therapies for ovarian cancer." (PMID 26413750, 2015).
melanoma (10 papers, 2016 to 2024). A malignant, usually aggressive tumor composed of atypical, neoplastic melanocytes. "Notably, MTSS1 has a closer association with melanoma progression where it plays a pivotal role in driving melanocyte metastasis, and elevated MTSS1 expression identifies a subgroup within primary melanomas associated with adverse prognosis." (PMID 39015503, 2024). "However, other studies have shown that MTSS1 expression may be associated with increased invasion and metastasis in subtypes of malignant melanoma, non-small cell lung (NSCLC) and breast cancer." (PMID 29497041, 2018). "Thus, loss of MTSS1 in G10 confirms its shift to a more aggressive melanoma." (PMID 27206673, 2016). "We also further illustrated the potential role of MTSS1 in melanomas." (PMID 39039072, 2024). "Interestingly, MTSS1 has been reported as the metastasis driver gene in a subset of human melanomas." (PMID 36768794, 2023). "Thus, our findings emphasized that MTSS1 might impact melanoma prognosis by regulating the actin cytoskeleton organization pathway." (PMID 39039072, 2024). "MTSS1/MIM-B is also found upregulated in the early stages of several cancers, including melanomas, head and neck squamous cell carcinoma, and lung cancer." (PMID 27230279, 2016).
colorectal cancer (9 papers, 2014 to 2023). A primary or metastatic malignant neoplasm that affects the colon or rectum. "Comparably, MTSS1 is a possible mechanistic target of miR-23a since increased MTSS1 expression is tightly linked with metastatic disease in tumors from colorectal cancer patients." (PMID 30224667, 2018). "In both cases, colorectal cancer cells and CCSCs, the overexpression of miR-23a was associated with inhibition of the metastasis suppressor 1 (MTSS1), consequently promoting cell migration and invasion." (PMID 27187371, 2016). "MTSS1/MIM over-expression is associated with enhanced cell migration, resulting in tumorigenesis, invasion and metastasis, and predicts poor prognosis in colorectal cancer, cervical carcinoma, and lung cancer." (PMID 27230279, 2016). "Consistent with our study, other studies reported that the positive expression rates of MTSS1 were significantly higher in advanced stages of colorectal cancer and cervical carcinoma." (PMID 27230279, 2016). "MTSS1 is a metastasis suppressor gene that is frequently hypermethylated in leukemia and prostate, gastric, and bladder cancers, excluding colorectal cancer, where there are no reports." (PMID 37614819, 2023). "Fusobacterium nucleatum, a gram-negative anaerobic bacillus, is mainly associated with colorectal cancer patients positive for the CpG island methylator phenotype, although hypermethylation in genes such as MLH1, CDKN2A, MTSS1, RBM38, PKD1, PTPRT, and EYA4 has also been described." (PMID 37614819, 2023).
gastric cancer (9 papers, 2010 to 2024). A primary or metastatic malignant neoplasm involving the stomach. "A loss of MTSS1 protein expression in gastric cancer has been associated with large tumor size, poor differentiation, deep invasion level, the presence of nodal metastasis, and poor outcome in patients who underwent gastrectomy." (PMID 24961659, 2014). "Given that gastric cancer is one of the most malignant cancers in the world and that tumor recurrence and metastases are the major causes of death in patients with gastric cancer, resulting in a poor prognosis of the disease, we set out to investigate the role of MTSS1 in gastric cancer." (PMID 20712855, 2010). "A gastric cancer study in a Chinese population also revealed that the expression levels of MTSS1 were increased in tissues adjacent to carcinoma, but were clearly reduced in cancer tissues." (PMID 25295101, 2014). "Among those genes with highly conserved binding sites, metastasis suppressor 1 (MTSS1) brought us lots of concern as it has been demonstrated to have prognostic value and anti-metastatic properties in breast cancer and gastric cancer." (PMID 22681717, 2012). "In this study, we observed significantly lower expression of MTSS1 in the nodal metastases of gastric cancers than that in primary tumors." (PMID 20712855, 2010). "Reverse transcription RT-PCR was used to evaluate MTSS1 expression level in 30 normal adjacent mucosa and 30 paired primary gastric cancer tissues." (PMID 20712855, 2010). "All these findings suggested that MTSS1 expression alone was a potential molecular marker for predicting outcome in patients who undergo gastrectomy for gastric cancer." (PMID 20712855, 2010). "In this study, we detected MTSS1 expression and explored its clinical significance in gastric cancer." (PMID 20712855, 2010). "Further functional investigations are worthwhile to explore the precise mechanism of the carcinogenic effect of MTSS1 with the goal of developing potential therapies targeting MTSS1 as an indicator for gastric cancer." (PMID 20712855, 2010). "Immunohistochemistry was performed using tissue microarrays containing gastric adenocarcinoma specimens from 1,072 Chinese patients with normal adjacent mucosa, primary gastric cancer and lymph node (LN) metastasis and specific antibody against MTSS1." (PMID 20712855, 2010). "Although these studies cited above suggested MTSS1 as a promising candidate biomarker and playing an important role in tumorigenesis, little is known about the function of MTSS1 in gastric cancer." (PMID 20712855, 2010). "Consistently, in our study, MTSS1 protein expression was lost more frequently in poorly differentiated tumors than in well-differentiated tumors, suggesting that MTSS1 is a differentiation marker for gastric cancer." (PMID 20712855, 2010). "In metastatic prostate cancer 34, gastric cancer 35 and renal cancer 36, MTSS1 may play an antimetastatic role in tumor progression." (PMID 32913477, 2020). "For example, in metastatic prostate cancer 8, gastric cancer 9 and renal cancer 10, MTSS1 may play an antimetastatic role in tumor progression." (PMID 32913477, 2020). "In our study, we sought to determine the expression of MTSS1 in resected gastric cancers and investigate the correlation of MTSS1 expression and clinicopathologic features and survival, in an attempt to discover the potential influence of MTSS1 on the development of gastric cancer." (PMID 20712855, 2010). "MTSS1 expression decreased significantly as gastric cancer progressed and metastasized, suggesting MTSS1 may serve as a useful biomarker for the prediction of outcome of gastric cancer." (PMID 20712855, 2010). "Aside from MTSS1 expression, survival analysis of other clinicopathological factors also revealed that lymph node metastases and clinical TNM stage were associated with prognosis of the patients with gastric cancer." (PMID 20712855, 2010). "MTSS1 expression may serve as a useful biomarker for the prediction of outcome of gastric cancer." (PMID 20712855, 2010).
gastric cancer (continued). "The putative tumor metastasis suppressor 1(MTSS1) is an actin-binding scaffold protein that has been implicated to play an important role in carcinogenesis and cancer metastasis, yet its role in the development of gastric cancer has not been well illustrated." (PMID 20712855, 2010). "MTSS1 and DSP are known tumor suppressor genes and are together with PPP1R14A, also methylated in lung-, colorectal- and gastric cancer." (PMID 24260260, 2013).